IFT43 (intraflagellar transport 43)
Description:
As a component of IFT complex A (IFT-A), a complex required for retrograde ciliary transport and entry into cilia of G protein-coupled receptors (GPCRs), it is involved in ciliogenesis. Involved in retrograde ciliary transport along microtubules from the ciliary tip to the base.
Synonyms: C14orf179; FLJ32173; MGC16028; CED3; RP81; SRTD18
Tractability: PROTAC: ubiquitination databases record sites on it.
Gene: Protein-coding gene on chromosome 14 (75,902,136 to 76,084,585, forward strand). Ensembl gene ENSG00000119650.
Subcellular location: Cytoplasm, cytoskeleton; Cell projection, cilium
Subcellular location (Human Protein Atlas): End piece; Microtubules; Primary cilium; Principal piece; Basal body; Centriolar satellite; Cytokinetic bridge; Mitotic spindle; Perinuclear theca
Pathways (Reactome):
Organelle biogenesis and maintenance: Intraflagellar transport
Gene Ontology:
Molecular function: protein binding
Biological process: cilium assembly; intraciliary retrograde transport
Cellular component: cilium; intercellular bridge; intraciliary transport particle A; microtubule cytoskeleton; ciliary tip; centriole; cytoskeleton
Genetic constraint (gnomAD): Loss-of-function variants: 28 observed, 29.94 expected, observed/expected ratio (o/e) 0.94, 90% interval 0.69 to 1.28. The upper end of that interval is the gene's LOEUF score, 1.28, which puts it in group 5 of 6, group 1 being the genes least tolerant of losing a copy. Missense variants: 244 observed, 250.83 expected, observed/expected ratio (o/e) 0.97, 90% interval 0.88 to 1.08. Synonymous variants: 85 observed, 94.62 expected, observed/expected ratio (o/e) 0.9, 90% interval 0.75 to 1.08.
Homologues: Orthologues: chimpanzee IFT43 (87% identical), macaque IFT43 (85% identical), rat Ift43 (77% identical), mouse Ift43 (76% identical), pig IFT43 (75% identical), guinea pig IFT43 (72% identical), rabbit IFT43 (70% identical), dog IFT43 (69% identical).
Diseases named in the same sentence as IFT43 in open-access papers:
IFT43 is named in the same sentence as 12 diseases in open-access papers, as found by Europe PMC text mining. Sharing a sentence is not in itself a finding about the gene and the disease. The quoted sentences say what the papers report.
Sensenbrenner syndrome (4 papers, 2013 to 2017). "Previously, homozygosity for an IFT43 mutation was reported in a single family with cranioectodermal dysplasia (CED), a disorder with skeletal abnormalities similar to ATD but with the additional findings of craniosynostosis and ectodermal abnormalities." (PMID 28400947, 2017). "Strikingly, we show that this differentiation process is defective in IFT43-defective Sensenbrenner syndrome cells, which are impaired in intraflagellar transport providing strong evidence that the differentiation step involves cilia-dependent signalling." (PMID 23516378, 2013). "For example, Sensenbrenner syndrome (also known as cranioectodermal dysplasia), a ciliopathy characterized by sagittal craniosynostosis with accompanying facial, skeletal, and ectodermal anomalies, is caused by mutations in the IFT-A genes IFT43, WDR35, IFT122, WDR19, and IFT140." (PMID 28724397, 2017). "Additionally, as controls for the analysis below, we examined primary fibroblasts derived from two Sensenbrenner Syndrome patients, which carry distinct defects in genes encoding primary cilia intraflagellar transport (IFT) proteins, namely WDR35 (also called IFT121) or IFT43." (PMID 23516378, 2013).
ciliopathies (3 papers, 2017 to 2023). "Human patients with mutations in IFT43 develop ciliopathies, demonstrating the importance of IFT43 in ciliogenesis or cilia-related function." (PMID 28207750, 2017).
nephropathy (1 paper, 2023). A nonspecific term referring to disease or damage of the kidneys. "Defects to the IFT-A complex of proteins (e.g., WDR35, IFT122, IFT43, IFT172, IFT140 and WDR19), can present with renal disease phenotypes such as chronic renal failure, NPHP, and renal cysts and, in some cases, isolated NPHP or NPHP-like nephropathy." (PMID 38292052, 2023).
IFT43 also shares sentences with these, for which no sentence is quoted: bacterial infection (1 paper); craniosynostosis (1); infection (1); infertile (1); muscle degeneration (1); nicotine dependence (1); pancreatitis (1); short rib-polydactyly syndrome (1); tauopathy (1).